ENSG00000239153
Synonyms: LOC124902826
Gene: Small nucleolar RNA gene on chromosome 11 (115,627,082 to 115,627,185, reverse strand). Ensembl gene ENSG00000239153.
Gene Ontology:
Biological process: RNA processing
Cellular component: nucleolus
Homologues: Paralogues in human: SNORD13 (85% identical), SNORD13D (83% identical), SNORD13P1 (83% identical), SNORD13E (81% identical), SNORD13P3 (81% identical).